IGF1 (insulin like growth factor 1)
Diseases named in the same sentence as IGF1 in open-access papers (continued):
Sharing a sentence is not in itself a finding about the gene and the disease.
Cachexia (continued). "Strategies based on the regulation of IGF-1 and the suppression of MSTN increase muscle growth and aid recovery from cachexia, and thus, drugs and inhibitors used to treat cachexia should have anti-inflammatory and appetite-stimulating properties." (PMID 35565236, 2022). "Myostatin and activin signaling, IGF-1/PI3K/AKT signaling, and JAK-STAT signaling are known to play roles in cachexia, and thus, these pathways are considered potential therapeutic targets." (PMID 35565236, 2022). "Altogether, research in animal models of cachexia highlights a potential link between lower IGF-1/AKT signaling in muscle and increased proteolysis during cachexia." (PMID 35319749, 2022). "In these cachexia models, the expression of ImpL2, the Drosophila homolog of mammalian IGFBP, is increased in tumor tissues, which disrupts both insulin and IGF-1 signaling." (PMID 35388147, 2022). "Cachexia is a complex wasting syndrome characterized by systemic inflammatory responses, elevated pro-inflammatory cytokines (IL-1, IL-6, and TNF-α), and remarkable effects on the IGF-1/Akt and NF-κB pathways." (PMID 36139760, 2022). "Next, in line with the changes in circulating IGF1 and IL6, we sought to investigate the cachexia-related molecular changes within the skeletal muscle of HCT116 and mHCT116 hosts." (PMID 31915140, 2020). "Circulating IGF-1 and muscle IGF-1 gene expression are generally decreased with wasting conditions including cachexia." (PMID 21949739, 2011). "Progressive decline in the secretion of growth hormone (GH) and its principal circulating and tissue mediator, insulin-like growth factor-1 (IGF-I), is one of the key pathophysiological mechanisms contributing to the cachexia of normal aging." (PMID 17662149, 2007). "A falsely elevated ratio may be seen in patients with sepsis or cachexia due to subnormal IGF-2 and IGF-1 levels in these cases." (PMID 38432069, 2024). "Thus, stimulating IGF-1 and blockading MSTN using natural compounds would promote muscle hypertrophy and provide a possible means of managing cachexia." (PMID 35565236, 2022). "In contrast to IGF-1 expression, AMPK activation was increased throughout later stages of cachexia, which might explain the decrease in mTOR signaling during extreme body weight loss." (PMID 21949739, 2011). "For the phenotype related to low levels of circulating IGF-1, no drugs were found in the drug-target databases that could increase IGF-1 levels and that have not been tested in clinical trials related to cachexia." (PMID 34832866, 2021). "However, increases in the IGF-1 and IGF-1 binding protein 3 (IGFBP-3) levels have been observed in adult patients with a decreased estimated GFR, and low IGF-1 have been reported in adult patients with CKD and cachexia." (PMID 27138941, 2016). "However, attempts to use IGF-1 to prevent cachexia have been limited due to the toxicity related both in terms of the action of IGF-1 increasing glucose blood levels and the relevant anabolic sequelae, including the major propensity to tumor growth of an IGF-1-enriched microenvironment." (PMID 36078078, 2022). "In cachexia, IGF-1 signaling is impaired, because cachexic muscle cells do not respond to basic IGF-1 stimulation." (PMID 35565236, 2022).
endothelial dysfunction (60 papers, 2010 to 2026). In vascular diseases, endothelial dysfunction is a systemic pathological state of the endothelium (the inner lining of blood vessels) and can be broadly defined as an imbalance between vasodilating and vasoconstricting substances produced by (or acting on) the endothelium. "The dysregulation of Nrf2 pathways in the vascular system in IGF-1 deficient mice promotes the endothelial dysfunction associated with increased apoptosis." (PMID 34943914, 2021). "Liver-specific knockdown of IGF-1 decreased Nrf2 levels in mouse aortas and was associated with exacerbation of endothelial dysfunction, increased oxidative stress, and apoptosis, mimicking the vascular aging phenotype." (PMID 32802505, 2020). "Patients with growth hormone and IGF-1 deficiencies exhibit endothelial dysfunction, reduced nitric oxide (NO) production, and high peripheral vascular resistance." (PMID 32477267, 2020). "In this study serum IGF-1 levels were found to be associated with endothelial dysfunction that predicts ED." (PMID 26823979, 2016). "Low IGF-1 serum concentrations were associated with high oxidative stress in the vasculature, potentially leading to endothelial dysfunction." (PMID 26823979, 2016). "In that study, cultured aorta segments of IGF-1-deficient mice treated with a panel of oxidative stressors showed attenuation in Nrf2-driven genes, leading to endothelial dysfunction, increased oxidative stress, and apoptosis." (PMID 24341939, 2014). "Therefore, this study aimed to investigate the aging-related insulin- and IGF-1-mediated endothelial dysfunction and antioxidant deficiency in SHRs." (PMID 34203897, 2021). "Endothelial dysfunction could be related to the process of oxidative stress, in which insulin growth factor 1 (IGF-1) deficiency and inflammation leads to a lower nitric oxide bioavailability." (PMID 31450572, 2019). "Importantly, previous studies demonstrate that IGF‐1 deficiency leads to endothelial dysfunction and impaired bioavailability of NO in the peripheral circulation (reviewed in Ungvari & Csiszar (2012))." (PMID 26172407, 2015). "Increased expression of DPP-4 was observed during endothelial dysfunction in the aortic valve which leads to degradation of insulin-like growth factor-1 (IGF-1) and increases osteogenic differentiation of vascular interstitial cells." (PMID 41335598, 2025). "Increased oxidative stress, leukocyte telomere length (LTL) shortening, endothelial dysfunction, and lower insulin-like growth factor (IGF)-1 concentrations reflect key molecular mechanisms of aging." (PMID 33989340, 2021). "This study demonstrated that the process of aging additively affected insulin- and IGF-1-mediated endothelial dysfunction mainly through impairing the PI3K-NOS-NO pathway in SHRs." (PMID 34203897, 2021). "Many studies involving various arterial districts (microvascular arteries of retina, kidney and brain, and major vessels as carotid and aorta) showed that GH/IGF-1 excess promotes endothelial dysfunction via several different mechanisms." (PMID 31396153, 2019). "GH treatment and subsequent increase in IGF-1 levels have been shown to improve endothelial dysfunction in rats." (PMID 23308239, 2013). "Its mode of action of cleaving insulin-like growth factor 1 (IGF-1) was found to counteract endothelial dysfunction by binding to high affinity binding sites in the endothelium which then triggers nitric oxide release." (PMID 20529285, 2010). "This feed-forward loop links IGF-1 signaling to worsening endothelial dysfunction." (PMID 41169887, 2025). "This could be mediated by the restoration of the circulating levels of IGF1, which are reduced at birth in the offspring of undernourished mothers and have been shown to improve endothelial dysfunction in rats." (PMID 38695077, 2024).
endothelial dysfunction (continued). "Structural Equation Modelling (SEM) was used to investigate the statistical inter-relationships between biomarkers related to inflammation, oxidative stress, insulin-like growth factor 1, expression of microRNA, fibrosis, and endothelial dysfunction and their impact on the clinical effects." (PMID 35381849, 2022). "This study demonstrated that the process of aging additively affected insulin- and IGF-1-mediated endothelial dysfunction in SHRs, which could be partly attributed to the reduced NO production and antioxidant deficiency." (PMID 34203897, 2021). "This study shows a relationship between decreased serum IGF-1 level and the presence and severity of ED, which may be postulated as evidence of endothelial dysfunction in ED." (PMID 26823979, 2016). "The lower IGF-1 and IGFBP-3 and higher HOMA-IR levels in the Stressed group might further support inactivation or downregulation of retinal glia insulin receptors and subsequent endothelial dysfunction or glaucoma risk." (PMID 33670473, 2021). "Our group has also reported signs of less endothelial dysfunction otherwise accompanying ageing, due to the intervention with selenium and coenzyme Q10, as seen from evaluation of the von Willebrand factor, and the plasminogen activator inhibitor-1 and the increase in IGF-1." (PMID 33317156, 2020). "The findings that in IGF‐1‐deficient mice, the L‐NAME‐sensitive, NO‐mediated portion of the neurovascular coupling response was decreased suggest that cerebromicrovascular endothelial dysfunction also contributes to neurovascular uncoupling in IGF‐1 deficiency, mimicking the aging phenotype." (PMID 26172407, 2015). "IGF-1 stimulates mitochondrial ROS production via PI3K/Akt and MAPK/ERK cascades, which in turn can activate NF-κB and promote inflammatory gene expression, further aggravating endothelial dysfunction." (PMID 41169887, 2025). "In contrast, supraphysiological IGF-1 levels are reported not to be protective, but rather evoke endothelial dysfunction (ED) and CVD." (PMID 32458292, 2020). "The vascular inflammation and endothelial dysfunction markers examined were plasminogen activator inhibitor-1 (PAI-1), vascular adhesion molecule-1 (VCAM), intercellular adhesion molecule-1 (ICAM), E-selectin, insulin-like growth factor-1 (IGF-1), and others." (PMID 23227034, 2012). "Nevertheless, the persistence of a negative trend between IGF-1 SDS and RHI supports the hypothesis that IGF-1 deficiency may play an independent role in endothelial dysfunction." (PMID 41374948, 2025). "GH and IGF-1 have various negative effects on the cardiovascular system like microvascular inflammation, oxidative stress, and endothelial dysfunction which may explain the development of cardiovascular complications." (PMID 36326330, 2022).
Sepsis (58 papers, 2007 to 2026). Sepsis is defined as life-threatening organ dysfunction caused by a dysregulated host response to infection. "Integrating the data on IGF1 and sepsis showed a significant causal association between IGF1 levels and sepsis incidence, and there were three associated SNPs." (PMID 41555186, 2026). "Due to its known effect on muscle protein synthesis and because septic patients had lower levels of IGF-1, IGF-1 has become an interesting target to prevent muscle loss during sepsis." (PMID 36904071, 2023). "Through its activation of the phosphoinositol-3 kinase pathway and phosphorylation of the X-linked inhibitor of apoptosis protein (XIAP), IGF-1 acts to protect Küpffer cells and counter the potentially lethal effects of sepsis." (PMID 33557137, 2021). "A multiple logistic regression analysis was used to obtain curves for the probability of developing ROP, based on the main factors linked with ROP, namely serum levels of IGF1 and presence of sepsis." (PMID 24523937, 2014). "Genetic prediction showed that IGF1 levels negatively correlated with the risk of sepsis." (PMID 41555186, 2026). "Further information regarding mortality risk in children with sepsis may derive from the evaluation of insulin-like growth factor 1 (IGF-1) and insulin-like growth factor binding protein 3 levels (IGFBP-3)." (PMID 39858517, 2025). "Also, another study, focusing on a new method to identify newborns at risk of ROP based on IGF1 levels and the presence of sepsis, further validates our approach by demonstrating a 100% negative predictive value for ROP screening." (PMID 39194926, 2024). "Previously, it has been shown that in chronic inflammatory conditions, like sepsis, increased GH and decreased IGF-1 levels are linked with disease severity, suggesting that these conditions may be termed GH resistance." (PMID 38892024, 2024). "Evidence also implicates IGF-1 in vascular protection, which might be beneficial in chronic cardiac insufficiency and in treatment of sepsis-associated cardiac dysfunction." (PMID 27423905, 2016). "However, administration of IGF-1 effectively attenuates the inhibition of protein synthesis in sepsis or trauma and further ameliorates the loss of muscle mass." (PMID 24204984, 2013). "IGFBP‐3 is the primary determinant of IGF‐1 levels, reflecting disruption in the GH/IGF‐1 axis during sepsis." (PMID 41555186, 2026). "Previous studies had demonstrated that the GH/IGF‐1 axis was severely disrupted in patients with sepsis." (PMID 41555186, 2026). "Animal models of endotoxemia and clinical studies have consistently shown that sepsis reduces circulating levels of both IGF-1 and IGFBP-3, as well as their hepatic gene expression." (PMID 40724799, 2025). "Low insulin-like growth factor 1 (IGF-1), secondary to poor nutrition or sepsis, further impairs VEGF activation." (PMID 39524166, 2024). "In an animal study model of sepsis, pretreatment with IGF-1 improved the bacterial clearance of P. aeruginosa in the liver and positively impacted survival." (PMID 36904071, 2023). "proved, in mice undergoing experimental sepsis, an inverse correlation between circulating concentrations of IGF-1 with bacterial translocation and migration to liver." (PMID 39816412, 2022). "Other factors that mediate muscle wasting in sepsis are hormones whose secretion is modified by sepsis, such as glucocorticoids and IGF-1." (PMID 35408999, 2022). "Previous research has shown that patients with sepsis have low levels of IGF-1 inversely correlated with enteric bacterial load." (PMID 34695658, 2021). "Serum IGF-1 is reduced in the acute phase of critically ill patients with sepsis and was inversely related with the severity of the sepsis." (PMID 34502376, 2021). "At 28 weeks PMA, IGF-1 was measured in six infants, of whom five had a recent history of sepsis and required an erythrocyte transfusion within 24 h of the blood sampling." (PMID 32131447, 2020).
Sepsis (continued). "The mechanism for the decrease in serum IGF-1 in sepsis includes a depression of growth hormone receptor expression in the liver, which is a consequence of increased circulating inflammatory cytokines." (PMID 32521790, 2020). "We applied our new method based on measurement of insulin-like growth factor 1 (IGF1) levels at 3 weeks of age and the presence of sepsis during the first 3 weeks of life." (PMID 33381481, 2020). "Exogenous GH administration in a sepsis-induced colitis rat model showed GH induced IGF-1 expression in the colon." (PMID 32349250, 2020). "IGF-1 therapy was selected because there was a reduction in serum IGF-1 in our past studies of sepsis and because IGF-1 is considered to be renal protective." (PMID 32521790, 2020). "Since the increase in blood levels of FGF-23 is known to associate with kidney failure, we further investigated the mechanisms leading to sepsis-induced decrease in blood levels of IGF-1." (PMID 31791247, 2019). "Since the increase in blood FGF-23 levels is known to associate with kidney failure, we further investigated the mechanisms leading to the sepsis-induced decrease in blood IGF-1 levels." (PMID 31791247, 2019). "Another important finding in our current study is the decreased blood levels of IGF-1 in sepsis patients and sepsis mice." (PMID 31791247, 2019). "In this regard, in addition to its role in stimulating the activity of kidney 1α-hydroxylase, IGF-1 can potentially ameliorate kidney and liver failure in sepsis patients." (PMID 31791247, 2019). "Our data showed that, indeed, the mRNA expression of IGF-1 was significantly suppressed in the livers of sepsis mice when compared to healthy control mice (1 ± 0.4 vs. 2.4 ± 1.7, p < 0.05)." (PMID 31791247, 2019). "Collectively, the increased FGF-23 levels, decreased IGF-1 levels, and decreased 1,25(OH)2D levels in blood worsen systemic inflammation and multi-organ failures in sepsis patients." (PMID 31791247, 2019). "Consistent with the suppressed IGF-1 production, blood levels of GH were significantly increased in sepsis mice (22.6 ± 4.0 vs. 1.8 ± 1.0 ng/mL, p < 0.01)." (PMID 31791247, 2019). "The importance of sepsis has previously been described, while the current study shows that its combination with IGF1 levels increases the accuracy of prediction of ROP." (PMID 24523937, 2014). "We performed a prospective study to establish a useful screening system for ROP prediction and we have determined that measuring serum levels of IGF1 at week three and the presence of sepsis have a high predictive value for the subsequent development of ROP." (PMID 24523937, 2014). "IGF‐1 levels decrease significantly in patients with sepsis, correlating with disease severity." (PMID 41555186, 2026). "Sepsis also affects the levels of IGF-1, which is crucial for normal early postnatal growth." (PMID 39942424, 2025). "On the other hand, IGF-1 levels are negatively correlated with sepsis severity." (PMID 39838305, 2025). "IGF-1 is lower in septic shock than in mild to moderate sepsis." (PMID 39838305, 2025). "However, there were more cases of sepsis in the IGF-1 treated group (38 vs. 25%), although the difference was statistically insignificant." (PMID 37648745, 2024). "The inhibitory effect of sepsis on IGF-1 expression in locomotor muscles is well known." (PMID 35408999, 2022). "Contrarily, when IGF-1 was administered to mice, bacterial translocation was reduced, and apoptosis of cecum epithelial cells previously seen in sepsis was prevented, thus demonstrating that IGF-1 also promotes the stability and survival of gastrointestinal cells." (PMID 39816412, 2022). "IGF-1 elevation in adulthood may correlate with increased cancer risk, conversely, IGF-1 treatment can provide a therapeutic protection in sepsis." (PMID 33557137, 2021). "Sepsis in humans and experimental sepsis in animals decrease both circulating IGF-1 and IGFBP-3." (PMID 34502376, 2021).